CD4 (CD4 molecule)
Diseases named in the same sentence as CD4 in open-access papers (continued):
Sharing a sentence is not in itself a finding about the gene and the disease.
Immunodeficiency (continued). "Mutation of NFKB2 (nuclear factor kappa B subunit 2) is associated with immunodeficiency, including the CD4+ or CD8+ T cell dysfunction but normal function and number of NK cells." (PMID 35341155, 2022). "The prevalence of the etiology of FUO in HIV-infected patients depends on their immune deficiency status, which is reflected by CD4 cell counts." (PMID 35042469, 2022). "Immunodeficiency associated with low CD4 counts also fuels the high TB incidence which compounds mortality in this vulnerable population." (PMID 35136596, 2022). "It follows from the immune deficiency argument that direct or surrogate markers of immune competence, such as the CD4 lymphocyte count or viral load, would better explain differences in the prevalence of an immunologically mediated disease." (PMID 36699973, 2022). "CD4/CD8 ratio of less than 1.0 should be aggressively investigated for HIV infection as well as other causes of immune deficiency." (PMID 35681174, 2022). "Variants associated with immune diseases point toward the role of CD4+ regulatory T cells (Treg cells)." (PMID 35591976, 2022). "In summary, KD's occurrence and development are significantly correlated with immune dysfunction—a decrease in the number of resting CD4+ memory T cells, which was caused mainly by the upregulated expression of IL2RB." (PMID 35924269, 2022). "False-positive findings were strongly linked with age, sex, comorbidity with diabetes or immune system diseases, neutrophil counts, lymphocyte counts, CD4 levels, and CD4/CD8 ratio." (PMID 36288019, 2022). "These immune dysfunction-associated noncoding enhancers act specific lineages of genetic programs in CD4+ T cell differentiation and are applied to control temporal gene regulation of stimulus response in disease." (PMID 35812386, 2022). "Collectively, our results show that NTM-PD is associated with immune dysfunction and exhaustion in CD4+ and CD8+ T cells, NK T cells, NK cells and monocytes." (PMID 36439147, 2022). "The newly discovered CD4+ T helper cells, Th9 and Th17 lymphocytes, have been confirmed to be closely associated with a variety of immune diseases." (PMID 35935994, 2022). "In human immunodeficiency virus (HIV) infected people, the immunodeficiency caused by reduced levels of CD4 (cluster of differentiation 4) T-lymphocytes, destroyed due to constant multiplication of the virus, increases the risk of infectious diseases." (PMID 34959511, 2021). "The study showed low vitamin D level was associated with decreased CD4 recovery after ARV therapy in HIV patients with severe immune deficiency." (PMID 33664952, 2021). "With emerging information on PLWH with COVID-19 disease, a more pronounced immunodeficiency, defined as a current CD4 count <350/μl and a low CD4 nadir, has been associated with an increased risk for severe COVID‐19 disease and mortality." (PMID 34611163, 2021). "Apart from these, immune deficiency is observed in HIV-infected patients because of decreasing the number of CD4+ lymphocytes which is actually the results of plasma membrane disruption and subsequent cell death." (PMID 34819855, 2021). "AIDS, which results from HIV, causes severe immunodeficiency, mostly affecting cell-mediated immunity, via infection and death of CD4+ T cells and impairment in the function of surviving helper T cells." (PMID 34696319, 2021). "In HIV (human immunodeficiency virus) infected people, the immunodeficiency caused by a reduced level of CD4 (cluster of differentiation 4) T-lymphocytes increases the risk of infectious diseases." (PMID 34959511, 2021). "The authors concluded that among a population of HIV-positive military veterans with a high prevalence of risk factors for CVD, immunodeficiency (CD4 cell count below 500 cells/mm3) or a detectable viral load raised the risk of developing LEAD even more." (PMID 33859308, 2021).
Immunodeficiency (continued). "While the HIV viral load is considered as a marker of the driving force of immunodeficiency, the CD4+ T-cell count reflects the degree of deficiency that has occurred." (PMID 33537915, 2021). "Immune deficiency accompanied by a decrease in CD4/CD8 lymphocyte count was also diagnosed in 25% of patients (Case 1) in Group B." (PMID 35011785, 2021). "As a result, we incorporated the use of Total Lymphocyte Count as a substitute for absolute CD4+ T cell counts for monitoring immune deficiency in HIV infected individuals from resource limited settings." (PMID 33836748, 2021). "Due to the immune deficiency and low CD4+ count, HIV patients are prone to actinomycetes infections." (PMID 34031507, 2021). "The characteristic loss of CD4+T cells that is thought to play a key role in the development of immunodeficiency." (PMID 33820568, 2021). "Chronic stress also promotes the development of tumors by causing immune disorders in the body, which decrease the numbers of CD4+ and CD8+ cells around tumors and reduce tumor necrosis factor, interferon and macrophage levels." (PMID 34988010, 2021). "HIV is a retrovirus, whose infection is characterized by a combination of clinical manifestations which are caused by the infection directly and killing of CD4+ lymphocytes, thus decreasing the natural defense mechanism leading and severe immunodeficiency." (PMID 33308188, 2020). "Both HIV-1 and SARS-CoV-2 infection share CD4+ T cell loss in association with disease outcome and immunodeficiency." (PMID 33384690, 2020). "In our study, ART-naïve HIV-infected patients especially those of male gender with severe immunodeficiency (CD4 cells < 200/mm3) had a significantly higher risk of periodontitis." (PMID 33308188, 2020). "In fact, CD is a T cell-mediated immune disease in which gluten-derived peptides activate the lamina propria CD4+ Teff cells, and these T-cell subsets can cause the intestinal tissue damages." (PMID 31952431, 2020). "Taken together, our study provides new insights into the role of TCR and CD28 costimulation in the activation and proliferation of human naive and memory CD4 T cells, and the influence of these stimuli on immune disease susceptibility." (PMID 33223527, 2020). "A low frequency of cervical CD4 T cells is likely to be associated with immune dysfunction and elevates the risk of acquiring an HPV infection." (PMID 33007050, 2020). "An individual's risk of cancer (and long-term immune dysfunction) is likely influenced by the CD4 nadir, perhaps indicative of a synergistic relationship between chronic inflammation and impaired immune surveillance." (PMID 31555284, 2019). "Progressive decline of CD4+T cells following HIV infection is a hallmark of disease progression resulting in HIV associated immune dysfunction." (PMID 30744575, 2019). "The human immunodeficiency virus (HIV) infects and destroys the CD4+ T cell, promoting a continuous loss of CD4+ T cells that leads to immunodeficiency, opportunistic diseases, and death." (PMID 30522500, 2018). "The low to borderline CD4 counts at ART initiation suggests immune-deficiency among co-infected patients, resulting in poor prognosis at ART initiation." (PMID 30133504, 2018). "The pathogenesis of HIV immunodeficiency is dependent on the cytopatic effects exerted by the virus against infected CD4+ T cells and to subsequent CD4+ T cell loss." (PMID 30459765, 2018). "This risk is associated with the degree of cell-mediated immune deficiency, particularly in patients with CD4+ T-cell count <200 cells/mm3." (PMID 29619261, 2018). "In this study, we found that HIV-associated immune dysfunction (as indicated by nadir CD4+ T cell count <200 cells/mm3) was associated with more than twofold greater likelihood of having AF/AFL even after adjustment for demographics and CVD risk factors." (PMID 29558525, 2018). "Specific bacterial taxa were associated with impaired CD4 T-cell reconstitution and persistent immune dysfunction following ART." (PMID 30250162, 2018).
Immunodeficiency (continued). "The risk factors for immune dysfunction/premature aging in the HIV-positive group HIV included advanced HIV disease with low CD4+ T cell count and the duration of antiretroviral therapy for those that had already received ART." (PMID 29351788, 2018). "Individuals with a missing initial creatinine value had higher CD4 counts, indicating a less advanced immune deficiency." (PMID 28931037, 2017). "Nadir CD4+ T-cell count reflects a profound immune deficiency in the past, and is also associated with chronic immune activation and persistent microbial translocation." (PMID 28749986, 2017). "Imbalance between the two types of CD4+ T cells which associated with immune system disorders is of vital importance in the pathogenesis of ACLF." (PMID 28194045, 2017). "Even though depletion of CD4 T cells is the hallmark of HIV-induced immune dysfunction, the virus causes many other immunological abnormalities within the CD4 T-cell compartment." (PMID 28445512, 2017). "The study confirmed the high incidence of NADE in this cohort and showed that these events were associated with persistence of profound immunodeficiency, i.e. very low CD4+ cell count under treatment." (PMID 27548257, 2016). "Cancer patients often suffer from immune deficiency, including a decrease in CD4+/CD8+ T cell ratio, especially during a long period of systemic chemotherapy." (PMID 27097970, 2016). "In this case report, the low CD4 count of Case 1 patient and the complicated medical conditions of Case 2 patient predisposed the patients to immunodeficiency, thus susceptible to the infections of F. khargensis." (PMID 27010640, 2016). "The degree of tryptophan depletion correlated with the decline in the CD4 count (r = 0.341; p = 0.005) and therefore with the degree of immune deficiency." (PMID 26887418, 2016). "The observation of higher IFN-γ levels with improved CD4+ T-cells differed to the results of previous studies which associated persistent immune dysfunction with poor recovery of CD4+ T-cells." (PMID 27935986, 2016). "The co-infected IHUs have elevated risk of immunodeficiency due to significantly depressed CD4 T-cell numbers." (PMID 26208212, 2015). "The majority of our cases represented newly diagnosed TB and presented in an advanced state of immune deficiency, with low CD4 T-cell counts." (PMID 25941570, 2015). "An interesting finding is that two-thirds of the HIV-infected patients had already been in a state of advanced immune deficiency (i.e. <200 CD4 cells/μL) by the time they were enrolled in HIV care." (PMID 26114436, 2015). "Severe immune deficiency of ≤73 CD4 cells/μL at enrolment in care was found to be the strongest predictor of attrition and adds to evidence of several other studies." (PMID 26114436, 2015). "The inverse association of benzene exposure on levels of CD4+ T cells is particularly notable given the established relationship between immune deficiency, various immune disorders, and NHL risk." (PMID 25748391, 2015). "Our study shows that, at the time of inpatient TB treatment initiation, most patients were at an advanced immune deficiency state as the median CD4 T-cell count was 102 cells/mm3." (PMID 25941570, 2015). "The CD4/CD8 ratio has typically been linked in elderly with a general state of immune dysfunction, where an inverted CD4/CD8 ratio is associated with short-time mortality." (PMID 26402620, 2015). "HIV causes rapid CD4+ T cell depletion in the gut mucosa, resulting in immune deficiency and defects in the intestinal epithelial barrier." (PMID 25166758, 2014). "CD4 count is a proxy for the extent of immune deficiency and declines in CD4 count are a measure of disease progression." (PMID 24831447, 2014). "We further investigated the relationship between severe immune deficiency (CD4<100/mm3) and severe vitamin D deficiency by testing different models comprising vitamin D (<10 ng/mL vs. ≥10 ng/mL) and several inflammatory markers." (PMID 24058636, 2013).
Immunodeficiency (continued). "We chose to study four different indices of disease severity that reflected not only the degree of HIV-associated immunodeficiency (CD4 cell counts) but also other important aspects of the disease process." (PMID 24168211, 2013). "Association between severe immune deficiency (CD4<100/mm3) and severe vitamin D deficiency (<10 ng/mL) : odds ratio of severe immune deficiency after adjustment for different inflammatory markers (N = 201 patients with inflammatory markers measurements)." (PMID 24058636, 2013). "Patients with 25(OH)D concentrations below 10 ng/mL had a more severe immune deficiency than patients with 25(OH)D≥10 ng/mL, since 18.8% vs. 10.7% had a CD4 count<100/mm3 (P = 0.04)." (PMID 24058636, 2013). "In previously published cases of HIV-associated PRES, all had similarly advanced immunodeficiency with seven of nine patients having CD4 counts <200 cells/μL while the remaining were <300 cells/μL." (PMID 23981526, 2013). "Increased susceptibility to brain infection was due to severe immunodeficiency at 8 wks p.i. and a marked increase in programmed death-1 (PD-1) expression on CD4+ and CD8+ T-cells." (PMID 23902750, 2013). "The HIV infection is uinque in causing depletion of CD4+ T-cells and induces profound cell-mediated immunodeficiency which permits dysregulated proliferation of B lymphocytes." (PMID 23114019, 2012). "While SIVsm infection in SM results in a nonpathogenic infection characterized by high levels of viremia in the absence of CD4 decline; infection of RM with SIVmac results in rapid loss of CD4 cells leading to immunodeficiency." (PMID 23202514, 2012). "Although highly variable diagnostic accuracy has been observed in different clinical populations, it is now clear that this assay has useful sensitivity for diagnosis of HIV-associated TB in patients with advanced immunodeficiency and low CD4 cell counts." (PMID 22536883, 2012). "Results were similar when adjusting for baseline immune deficiency using a separate category for missing CD4 cell count or restricting the analysis to the complete dataset." (PMID 23285204, 2012). "CD4+ T cells were shown to play a role in protecting neurons in general, and MN in mSOD1 mice in particular, while immune deficiency in these mice resulted in reduced life expectancy." (PMID 21829620, 2011). "Acute FIV-C36 infection is characterized by very high peak viremia and substantial CD4+ T cell loss, leading to early symptoms of immunodeficiency." (PMID 21364928, 2011). "While some studies suggested that IGRA were less influenced by HIV infection other studies reported loss of sensitivity with severe immunodeficiency, in particular when CD4 cell counts were less than 100 cells/μl." (PMID 22085801, 2011). "Such R5 virus variants appeared in patients with severe immunodeficiency, as evidenced by low CD4+ T-cell count at time of virus isolation." (PMID 21698221, 2011). "The viraemia, determined by different grades of virus burden from 33 000 cpml (based on the median for all HIV positive study individuals), and levels of immune deficiency, determined by CD4+ counts were assessed in the four subgroups." (PMID 21999928, 2011). "Recently, adjuvant recombinant human IL-7 (rhIL-7) was demonstrated to be effective in sustaining CD4+ recovery in HIV-positive patients with different degrees of immune deficiency." (PMID 21209878, 2010). "Infection with human immunodeficiency virus (HIV) leads to progressive loss of CD4 T cells and clinical immunodeficiency due to CD4 T cell lymphopenia." (PMID 20689824, 2010). "Age and prolonged periods of immune deficiency prior to successful HAART are risk factors for incomplete CD4 cell recovery." (PMID 21044307, 2010). "The information on the reference ranges of CD4+ T cell counts in a population is required for the application in the clinical settings such as various immune deficiencies." (PMID 21245613, 2010).
Immunodeficiency (continued). "Factors associated with ADCs were immunodeficiency and lower CD4 cell count, while among NADCs overall and for NADCs-IUR, factors were older age and not currently receiving antiretroviral treatment." (PMID 21143940, 2010). "Severe clinical status, unavailable clinical status, severe immunodeficiency and missing baseline CD4 cell result were independently associated with increased probabilities of mortality." (PMID 21108804, 2010). "The CD4+ T lymphocytes are the crucial cells in the cascade of events in forming immune response to the foreign antigen and hence monitoring the CD4+ T cell counts to understand the extent of immune deficiency is a common practice." (PMID 21245613, 2010). "The defining feature of HIV-associated disease is the slow loss of CD4+ T cells in the chronic phase of infection and resulting immunodeficiency." (PMID 19360097, 2009). "Conditional virus-free killing of activated CD4+ T cells, which include both memory and regulatory subsets, was directly responsible for the development not only of immune deficiency, but also of activation." (PMID 19943952, 2009). "Here we report that, in a virus-free mouse model, conditional ablation of activated CD4+ T cells, the targets of immunodeficiency viruses, accelerates their turnover and produces CD4+ T cell immune deficiency." (PMID 19943952, 2009). "Continuous viral replication causes the loss of CD4+T cells and progression to immunodeficiency in infected individuals." (PMID 19272132, 2009). "Collectively, our results support a model for HIV pathogenesis in which immune deficiency and activation originate from virus-mediated killing of memory and regulatory CD4+ T cells, respectively." (PMID 19943952, 2009). "Advanced pre-treatment immunodeficiency has also been found to be associated with diminished capacity for restoration of CD4 cell counts and CD4 cell functional responses after ART initiation." (PMID 19630949, 2009). "We therefore propose activated CD4+ T cell killing as a common etiology for both immune deficiency and activation in HIV infection." (PMID 19943952, 2009). "In patients with HIV infection, on the other hand, the selective loss of CD4+ T cells apparently triggers profound immunodeficiency, often leading to fatal infection, AIDS-defining illnesses and, ultimately, death." (PMID 18974880, 2008). "This is contrary to previous reports that advanced pre-treatment immunodeficiency is associated with diminished capacity to restore quantitative and functional CD4 T cell responses during antiretroviral therapy." (PMID 18957083, 2008). "For each EPI vaccine, HIV-infected children with severe immunodeficiency (CD4+ T-cell percentage <25%) had a significantly higher risk than HIV-exposed uninfected children of having low antibody levels." (PMID 18060056, 2007). "Underexpressed SDHD and CTNS are associated with immunodeficiency through curbed monocyte and CD4+ T cell -induced immunoregulation, respectively." (PMID 16956415, 2006). "CD4+ T cells harbor a disproportionate enrichment of immune disease risk loci and represent the primary cellular context for immune disease biology, yet the genes and regulatory programs these variants affect remain largely unknown." (PMID 41959477, 2026). "Since all four endemic HCoVs are encountered for the first time early in life, we suggest that the reactivation of immune memory upon (re)infection provides the “normal” short lived protection in people who later in life acquired a CD4 T-cell mediated immune deficiency." (PMID 40531922, 2025). "Therefore, it is more common in individuals with immune deficiencies, much like our patient, who presented with a low CD4 count." (PMID 41425515, 2025). "The observed decrease in the frequency of TIGIT-positive T cells across all CD4+ subsets may indicate a broader systemic immune deficiency." (PMID 41465029, 2025).